EPO (erythropoietin)
Diseases named in the same sentence as EPO in open-access papers (continued):
Sharing a sentence is not in itself a finding about the gene and the disease.
anemia (continued). "One study showed improved erythropoietin-resistant anemia following carnitine supplementation in 12 patients on PD." (PMID 31689941, 2019). "Transforming Growth Factor-β Inhibitors Erythropoietin induction by transforming growth factor (TGF)-β inhibition is a very recent development in the possible treatment of anaemia, and in particular for myelodysplastic syndromes." (PMID 30411235, 2019). "HIF is the major transcription factor for the EPO gene and represent a novel therapeutic approach to the treatment of anemia in CKD, which mimics the natural hypoxic response, by inhibiting prolyl-hydroxylase (PHD) enzymes." (PMID 29569190, 2019). "Because EPO is required for erythropoiesis, gene-modified mouse lines lacking EPO production exhibit embryonic lethality due to severe anemia." (PMID 31798631, 2019). "Androgenic steroids reverse anemia by stimulating erythropoietin, increasing iron use and reversing telomere loss." (PMID 29335406, 2018). "Consistently, leptin values were found to be a predictor of EPO responsiveness in people with kidney failure with anemia." (PMID 30294279, 2018). "Anaemia was defined by World Health Organization criteria taking into consideration erythropoietin use." (PMID 30290796, 2018). "Anemia can also be attributed to a decline in endogenous erythropoietin (EPO) production (e.g., during concurrent chronic kidney disease) or a reduction in bone marrow response to EPO." (PMID 30274354, 2018). "Among 49 patients who received ribavirin, folic acid and/or erythropoietin were added for anaemia in 11 (22.4%) and in 1/49 (2.04%) ribavirin was stopped for the same reason." (PMID 30326844, 2018). "As other means to treat anemia in critically ill, such as supplementation of recombinant erythropoietin, have shown benefit, but also harm, correction of anemia is usually done by blood transfusions." (PMID 29717382, 2018). "Anemia management through recombinant human erythropoietin (rhEPO) or erythropoiesis stimulating agents (ESAs) greatly benefits patients with CKD by improving their debilitating symptoms, and relieving them from dependence on blood transfusions." (PMID 29415057, 2018). "The injection of erythropoietin or GM-CSF is currently performed to treat anemia and granulocytopenia, respectively." (PMID 29970866, 2018). "Here we show that P38α restrains erythropoiesis in mouse and human erythroblasts independently of EPO by integrating apoptotic signals during recovery from anemia." (PMID 30158520, 2018). "For example, as erythropoietin stimulates proliferation of erythroid progenitors, patients whose anemia is characterized by defects in late-stage erythropoiesis are resistant to erythropoietin therapy." (PMID 29433555, 2018). "One of the most relevant clinical events in CKD is the anaemia produced by a decreased erythropoietin (EPO) production." (PMID 28857467, 2018). "Because of multiple side effects (anemia, asthenia, infections, and reduction of kidney functions - palliated by treatment with erythropoietin), treatment was stopped after 16 weeks." (PMID 29510685, 2018). "Preliminary evidence came from both clinical development of PHD enzyme inhibitors and experimental research suggests that augmenting HIF signaling to stimulate EPO production is an attractive strategy for the treatment of anemia of CKD." (PMID 30108502, 2018). "It is expressed on red blood progenitor cells, and plays (through EPO stimulation) a central role in the rapid expansion of erythroid progenitors in response to anemia and hypoxic stimuli in vivo." (PMID 29738538, 2018). "Artunc and Risler measured endogenous EPO concentrations in 500 patients with varying degrees of anemia and chronic kidney disease (ranging from CKD 1 to CKD5, where CKD 5 includes end-stage renal disease)." (PMID 29668766, 2018). "Of special clinical significance is our model simulation of anemia in CKD patients with insufficient erythropoietin and treatments with rEpo and iron dextran infusion." (PMID 29659573, 2018).
anemia (continued). "The expected compensatory response to anemia is a heightened rate of erythropoiesis by an exponentially increased EPO production in kidneys." (PMID 30108502, 2018). "Because of the prevalence of anemia in TBI patients and associated worse outcomes, administration of erythropoietin (EPO) was evaluated after head injury." (PMID 30719019, 2018). "Instead, his younger sister, who shared the same genotype and clinical picture, was treated with recombinant human EPO obtaining complete remission of anemia." (PMID 29191945, 2018). "Recent studies propose mathematical models to better predict the dosing strategy of recombinant erythropoietin (rEpo) used to treat anemia in patients with chronic kidney disease (CKD)." (PMID 29659573, 2018). "Partial correction of anemia with erythropoietin was shown to reduce insulin resistance as well as reduce insulin secretion." (PMID 28739553, 2018). "Of specific clinical value is the model simulation of anemia in CKD patients with insufficient erythropoietin and treatments with rEpo and iron dextran infusion." (PMID 29659573, 2018). "Hepatic EPO mRNA was elevated to the comparable levels at P7 and P14 reflecting the same degree of anemia." (PMID 29535446, 2018). "On the other hand, since the 1990s, the development of recombinant human erythropoietin has represented an important alternative to blood transfusions for treating anemia." (PMID 30274354, 2018). "Recombinant human erythropoietin has been shown to improve anemia in experimental animals and humans." (PMID 29692726, 2018). "Primarily, in regard with the mucosal and glandular involvement, the most common oral finding in dialyzed patient is pallor of the mucosa due mainly to anemia (reduced erythropoietin synthesis)." (PMID 30538746, 2018). "Limited iron availability for erythropoiesis can contribute to both anemia and EPO hyporesponsiveness." (PMID 30108502, 2018). "Previous studies analyzing the endogenous EPO levels in CKD patients with anemia and in patients with chronic heart failure (CHF) indicate that, in addition to relative EPO deficiency, bone marrow response to endogenous EPO is inhibited in these patients." (PMID 30108502, 2018). "Intravenous iron should be the first line treatment in patients with moderate-severe anaemia, in patients with active disease, in patients with poor tolerance to oral iron and when erythropoietin agents or a fast response is needed." (PMID 30544934, 2018). "EPO-induced antibodies neutralize all exogenous recombinant EPO and cross-react with endogenous EPO, leading to severe sudden onset anaemia." (PMID 29325166, 2018). "As an example, the human erythropoietin (EPO), a glycoprotein used in the treatment of anemia contains three N-glycans." (PMID 29710826, 2018). "There are multiple potential mechanisms in anemia associated with MDS, such as poor response of erythropoietin (EPO), altered GDF11-mediated Smad2/3 signaling, and gene mutation." (PMID 29967662, 2018). "Patients with chronic kidney disease (CKD) usually exhibit severe anemia complications because their kidneys cannot produce sufficient erythropoietin (EPO)." (PMID 30231592, 2018). "Although the anemia has a multifactorial origin, this patient's anemia may haveoriginated from her kidney disease, since the progression of the disease isaccompanied by a decrease in erythropoietin - which causes hypoproliferation of redblood cells, leading to normocytic and normochromic anemia." (PMID 29944158, 2018). "Previous studies reported lower serum EPO levels, smaller spleen size, and lower RBC transfusion frequency were associated with higher anemia response rates." (PMID 29335406, 2018). "While erythropoietin (EPO) constitutes the major treatment for anemia, a range of anemic disorders remain resistant to EPO treatment." (PMID 30158520, 2018). "EPO is a common treatment option for anemia patients and has a good safety profile when carefully monitored." (PMID 30400939, 2018).
anemia (continued). "Inflammation also contributes to anemia and erythropoietin resistance, mediated by decreased erythropoietin production." (PMID 30741617, 2018). "In these patients, pale tissues resulting from anemia or erythropoietin administration exhibited lower gingival inflammation." (PMID 29849971, 2018). "The increase we observed in EPO levels is presumably reflective of an increase in tissue hypoxia resulting from the anemia that accompanies thalassemia." (PMID 30064480, 2018). "EPO is commonly used in the treatment of anemia and has a good safety profile when carefully monitored." (PMID 29673379, 2018). "Anemia of CKD is thought to be due to impaired renal erythropoietin (EPO) synthesis, since the kidney’s tubulointerstitial cells are the main synthesis site for this hormone after birth." (PMID 29738538, 2018). "A blunted erythropoietin response to anaemia, eryptosis (premature death of red blood cells), neocytolysis (removal of newly formed erythrocytes), injury to red cell membranes and haemolysis can occur in sepsis." (PMID 29724246, 2018). "Management of patients with chronic kidney disease involves addressing anemia from impaired erythropoietin secretion." (PMID 30340570, 2018). "Previous clinical evidence showed that regular supplementation of A. sinensis improved anemia in a hemodialysis patient who was resistant to recombinant human EPO (rhEPO) therapy." (PMID 30108502, 2018). "The mechanism of rejection mediated anaemia is likely multifactorial, with both reduced erythropoietin production and inflammation-related erythropoietin resistance at play." (PMID 30290796, 2018). "Our patient had been treated with erythropoietin-stimulating factor for severe anemia preceding and following his coronary artery bypass graft surgery." (PMID 29429414, 2018). "In fact, treatment with human recombinant EPO (rhEPO) significantly improves the anaemia of these patients." (PMID 28857467, 2018). "Anemia is a complication of chronic kidney disease (CKD) that arises due to the malfunction of erythropoietin (EPO) production as kidney function declines." (PMID 29374477, 2018). "The discovery of EPO, a hormone principally produced by the peritubular interstitial cells of the kidney, revolutionized the treatment of anemia in chronic kidney disease patients." (PMID 30719019, 2018). "Anemia can be controlled by the interruption of the administered drugs and the prescription of erythropoietin." (PMID 30274298, 2018). "The present study reports that oral administration of ASP effectively corrects anemia by stimulating renal and hepatic EPO production and increasing iron availability in an adenine-induced rat model of renal failure." (PMID 30108502, 2018). "Anemia is a known driver for hypoxia inducible factor (HIF) which leads to increased renal erythropoietin (EPO) synthesis." (PMID 29738538, 2018). "The model also comprises reticulocytosis (up to 475%) on day 7 after injection accompanied by higher EPO levels as a body defensive reflex action against the induced anemia." (PMID 30328935, 2018). "We then studied the therapeutic effectiveness of ASP in an adenine-induced rat model of CKD that developed renal damage, anemia, inflammation, impaired EPO production, inactivation of EPO receptor signaling and disordered iron metabolism." (PMID 30108502, 2018). "Given this, correction of preoperative anemia by stimulating erythropoiesis through administration of iron and recombinant erythropoietin among other techniques has also been suggested." (PMID 28830388, 2017). "In this study, anemia is only transient and can be further mitigated with a specific dose of erythropoietin (EPO)." (PMID 28380460, 2017).
anemia (continued). "Recent basic science studies have suggested that renal interstitial fibroblasts produce erythropoietin in response to hypoxia or anaemia." (PMID 29178888, 2017). "Any patients will eventually require treatment with erythropoietin or similar products that are given by injection.Over the last few years, several iron and erythropoietin products have been licensed for treating anaemia in chronic kidney disease patients." (PMID 29191165, 2017). "Subjects with chronic kidney disease (CKD) often develop anemia because of decreased production of EPO resulting in insufficient erythropoiesis." (PMID 28077085, 2017). "In the present research, dialysis patients who suffered from anemia despite the consumption of erythropoietin and iron or other necessary compounds, were conducted to bone marrow aspiration and anti-body against erythropoietin." (PMID 28042550, 2017). "ESRD patients are in the state of micro inflammation, which is closely related to vascular sclerosis, anemia, erythropoietin resistance, malnutrition, and infection." (PMID 28164733, 2017). "In our study, low serum EPO levels for the grade of anemia were observed in women with anemia of chronic disease." (PMID 29348938, 2017). "Recombinant human erythropoietin is used for anemia, especially the treatment of anemia related to chronic kidney disease, and HIV." (PMID 28959352, 2017). "Since EPO is commercially available in the form of recombinant human EPO (rhEPO) and widely used in the treatment of anemia now, it is very important to identify its other therapeutic potentials or mechanisms of action." (PMID 29201007, 2017). "Although erythropoietin (EPO) has been used as an effective treatment for ESRD patients with anemia, a large number of patients still present poor responses to EPO treatment." (PMID 28697735, 2017). "Although recombinant human EPO is an effective treatment for anemia, adverse reports of decreased survival in some groups of cancer patients in Phase III trials led to a decline in its use from 2007 onwards." (PMID 28418910, 2017). "Several studies indicate that the Jak/Stat signaling pathway regulates the functions of cytokines, including erythropoietin, thrombopoietin, and granulocyte colony-stimulating factor during the treatment of anemia." (PMID 28683082, 2017). "The main reason for anemia in renal failure patients is the insufficient erythropoietin production by the kidneys." (PMID 28747155, 2017). "This phenomenon, combined with a downregulation of EPO production related to the increase in blood oxygen content and tissue oxygenation delivery following birth, leads to the so-called physiologic anemia of infancy." (PMID 29067568, 2017). "Alpha epoetin (EPO) and some other similar drugs have become the standard treatment for anemia in CKD patients." (PMID 28487874, 2017). "By blocking PHDs, these reagents induce the stabilization and accumulation of HIFs to stimulate EPO production and effective erythropoiesis to reduce anemia in CKD." (PMID 28468297, 2017). "Erythropoietin (EPO) is a heavily glycosylated hormone whose recombinant forms are used for treatment of anaemia." (PMID 28706253, 2017). "Common clinical practice treatment options of anaemia in patients with HF, which might be considered after exclusion of treatable/reversible causes (e.g., gastrointestinal bleeding), include application of erythropoietin and its derivatives, blood transfusions, or iron administration." (PMID 28229219, 2017). "EPO is an essential hormone for erythrocyte production and so, anemia commonly occurs in people with end stage renal disease (ESRD)." (PMID 28158274, 2017). "One hundred and twenty-nine subjects (56%) received prior anaemia therapy including androgenic steroids 43 (19%), corticosteroids 67 (29%), erythropoietin 81 (35%) and other therapies." (PMID 27773929, 2017). "Inhibition of erythropoietin (EPO) production induced by inflammatory cytokines contributes to the etiology of critical illness anemia." (PMID 28335733, 2017).
anemia (continued). "The cloning of the EPO gene allowed treatment of anemia in CKD patients by stimulating erythropoiesis with rHuEpo or other erythropoiesis stimulating agents (ESAs)." (PMID 28077085, 2017). "Prescription of recombinant erythropoietin (rHu-EPO) is the main step in treatment of anemia in these patients." (PMID 28042550, 2017). "Compared with ESAs, PHIs, as HIF stabilizers, demonstrated good effectiveness in treating CKD-related anemia with a comprehensive effect on replenishing endogenous EPO, decreasing hepcidin, and improving the bioavailability of iron." (PMID 29404328, 2017). "Accordingly, EPO has been applied in clinical settings for the prevention and management of perioperative anemia." (PMID 29201007, 2017). "The aim of this study was to determine the prevalence of PRCA due to antibodies in dialysis patients with resistant anemia who received erythropoietin." (PMID 28042550, 2017). "Patients and Methods: Thirty-nine ESRD patients with erythropoietin-resistant anemia were assigned to two groups, the treatment and the control groups." (PMID 28487874, 2017). "Anemia has been recognized as a well-documented risk factor in CHF, the potential mechanisms of which include inflammatory stress, inadequate production of erythropoietin, and the impact of comorbidities." (PMID 29038615, 2017). "Recombinant human EPO is currently used clinically for the treatment of anemia in patients with end-stage renal disease, and in certain cancer patients suffering from anemia induced either by the tumor itself or by chemotherapy." (PMID 28871174, 2017). "Anemia required high-cost outpatient care across all countries except for Germany due to use of erythropoietin and/or blood transfusions." (PMID 26721505, 2017). "Anemia is a common complication of chronic renal failure due to reduce erythropoietin production by kidneys." (PMID 28042550, 2017). "EPO has been widely used as an anti-anemia agent in patients with end-stage renal disease since 1987." (PMID 29047386, 2017). "One of the major differentiating features of the two, apart from history of treatment with EPO, would be that pure erythroid leukaemia presents with severe anaemia and circulating blasts whereas EPO-treated patients will have their anaemia corrected." (PMID 28144286, 2017). "The treatment of anaemia with erythropoietin-stimulating agents (ESA) in ESKD has revolutionised its treatment, but its use has been tempered by higher risks of cardiovascular morbidity and mortality." (PMID 29178879, 2017). "In this study, the iron status of serum ferritin <90 ng/mL and transferrin saturation ≥20% was optimal in hemodialysis patients receiving recombinant human erythropoietin for anemia therapy." (PMID 28662118, 2017). "Anemia is common in breast cancer patients and can be treated with blood transfusions or with recombinant erythropoietin (EPO) to stimulate red blood cell production." (PMID 28418910, 2017). "A diminished oxygen (O2) content due to anemia or hypoxaemia is the physiologic stimulus for EPO synthesis." (PMID 28335733, 2017). "While EPO can overcome anemia, the impact of hemolysis, such as hyperbilirubinemia, still needs further evaluation." (PMID 28380460, 2017). "The most frequent extracellular manifestation in RA occurring due to decrease in Hb and RBC levels is anemia, which ensues from decreased levels of erythropoietin and reduced plasma iron, induced by IL-1." (PMID 28720131, 2017). "Hemorheological studies have been performed to explain the consequences of anemia in patients with ESRD, who mostly use erythropoietin to cure anemia caused by the low production of EPO." (PMID 28158274, 2017). "Use of erythropoietin products to treat anemia also resulted in higher costs in Italy, France, Spain, and the Netherlands (over €1000 more)." (PMID 26721505, 2017). "Anemia is a common problem for patients suffering from ESRD due to the insufficiency of erythropoietin production." (PMID 28158274, 2017).